EGFLAM (EGF like, fibronectin type III and laminin G domains)
Description:
Involved in both the retinal photoreceptor ribbon synapse formation and physiological functions of visual perception. Plays a key role in the synaptic organization of photoreceptors by mediating transsynaptic interaction between alpha-dystroglycan and GPR179 on the postsynaptic membrane. Necessary for proper bipolar dendritic tip apposition to the photoreceptor ribbon synapse. Promotes matrix assembly and cell adhesiveness.
Synonyms: AGRINL; AGRNL; PIKA; FLJ39155
Tractability: Antibody: UniProt places it where antibodies can reach, with medium confidence; UniProt predicts a signal peptide or a membrane-spanning region; its Gene Ontology location is reachable by antibodies, with medium confidence. PROTAC: ubiquitination databases record sites on it.
Gene: Protein-coding gene on chromosome 5 (38,258,409 to 38,465,480, forward strand). Ensembl gene ENSG00000164318.
Subcellular location: Secreted, extracellular space, extracellular matrix; Synaptic cleft; Presynaptic active zone
Gene Ontology:
Molecular function: protein binding; molecular adaptor activity; calcium ion binding; glycosaminoglycan binding
Biological process: nervous system development; signal transduction; synapse assembly
Cellular component: basement membrane; non-collagenous component of basement membrane; non-collagenous component of interstitial matrix; photoreceptor ribbon synapse; plasma membrane; presynaptic active zone; synapse; synaptic cleft; extracellular matrix; interstitial matrix; trans-synaptic protein complex
Genetic constraint (gnomAD): Loss-of-function variants: 76 observed, 110.79 expected, observed/expected ratio (o/e) 0.69, 90% interval 0.57 to 0.83. The upper end of that interval is the gene's LOEUF score, 0.83, which puts it in group 3 of 6, group 1 being the genes least tolerant of losing a copy. Missense variants: 1,255 observed, 1,327.7 expected, observed/expected ratio (o/e) 0.95, 90% interval 0.9 to 0.99. Synonymous variants: 502 observed, 505.85 expected, observed/expected ratio (o/e) 0.99, 90% interval 0.92 to 1.07.
Homologues: Orthologues: chimpanzee EGFLAM (99% identical), macaque EGFLAM (98% identical), mouse Egflam (88% identical), rat Egflam (88% identical), dog EGFLAM (88% identical), guinea pig EGFLAM (87% identical), tropical clawed frog egflam (66% identical), pig EGFLAM (66% identical), zebrafish EGFLAM (58% identical), rabbit EGFLAM (57% identical). Paralogues in human: ATRN (15% identical), ATRNL1 (15% identical), MEGF8 (15% identical), LAMA5 (14% identical), LAMA3 (14% identical), LAMA2 (13% identical), LAMA1 (12% identical), LAMB1 (11% identical), LAMB2 (11% identical), HSPG2 (11% identical), LAMC3 (11% identical), LAMB4 (11% identical), and 15 more.
Diseases named in the same sentence as EGFLAM in open-access papers:
EGFLAM is named in the same sentence as 14 diseases in open-access papers, as found by Europe PMC text mining. Sharing a sentence is not in itself a finding about the gene and the disease. The quoted sentences say what the papers report.
mastitis (2 papers, 2017 to 2020). Inflammation of breast tissue during lactation or postpartum due to an obstructed duct or infection. "The gene EGFLAM was also located in a region where four QTLs related to somatic cell count, bacterial milk count and clinical mastitis were described." (PMID 32605032, 2020).
gastric cancer (1 paper, 2024). A primary or metastatic malignant neoplasm involving the stomach. "EGFLAM showed high levels of expression in normal tissues and diverse levels in gastric cancer patients, ranging from undetectable low to moderate to high levels." (PMID 38656888, 2024).
glioblastoma (1 paper, 2025). The most malignant astrocytic tumor (WHO grade IV). "EGFLAM also has functions that have been associated with glioblastoma and cancer cell proliferation." (PMID 40822650, 2025). "Mouse models that knocked down the function of EGFLAM showed a reduction in the proliferation, migration and tumor cell invasion in glioblastoma lesions." (PMID 40822650, 2025).
muscular dystrophy-dystroglycanopathy (1 paper, 2020). "The gene EGFLAM has been associated with Adiaspiromycosis and Muscular Dystrophy-Dystroglycanopathy." (PMID 32831014, 2020).
non-Hodgkin lymphoma (1 paper, 2022). Distinct from Hodgkin lymphoma both morphologically and biologically, non-Hodgkin lymphoma (NHL) is characterized by the absence of Reed-Sternberg cells, can occur at any age, and usually presents as a localized or generalized lymphadenopathy associated with fever and weight loss. "This SNP was mapped to the EGFLAM (EGF Like, Fibronectin Type III and Laminin G Domains) gene which has been associated with ovarian cancer, non-Hodgkin lymphoma, and Glioblastoma40." (PMID 35459784, 2022).
xerostomia (1 paper, 2022). Dryness of the mouth resulting from reduced salivary secretion. "EGFLAM, a protein coding gene which plays a role in matrix assembly and cell adhesiveness was associated with higher risk of reporting moderate to severe xerostomia." (PMID 35459784, 2022). "The most prominent findings in our study included potential associations of ANTXR1, RTP1, GLT1D1, NLRP9, and EGFLAM genes with xerostomia." (PMID 35459784, 2022).
cancer (5 papers, 2018 to 2025). A tumor composed of atypical neoplastic, often pleomorphic cells that invade other tissues. "The overexpression of EGFLAM is enriched in pathways including focal adhesion, gap junction, cancer, VEGF signaling pathway, and others." (PMID 38656888, 2024).
EGFLAM also shares sentences with these, for which no sentence is quoted: cervical cancer (2 papers); thyroid cancer (2); tumor (2); COVID-19 (1); infection (1); ovarian carcinoma (1); respiratory disease (1).